IDH1 (isocitrate dehydrogenase (NADP(+)) 1)
Diseases named in the same sentence as IDH1 in open-access papers (continued):
Sharing a sentence is not in itself a finding about the gene and the disease.
chronic myeloid leukemia (5 papers, 2012 to 2025). "In the chronic myeloid leukemia model (K562Dox) the following 4 DEPs were found to be involved in the GSH metabolism pathway (G6PD, PRDX2, IDH1 and 6PGD), 3 DEPs in the PPP pathway (G6PD, ALDOC and 6PGD) and 2 DEPs in the glycolysis pathway (ALDOC and PKM2)." (PMID 28303926, 2017). "Mutations in TFs and ERs are not major events in chronic myeloid leukemia (CML), which is triggered by the BCR-ABL1 fusion; however, mutations in ERs such as ASXL1, IDH1/2 and TET2 may participate to CML progression to AML." (PMID 22823977, 2012).
hepatoma (5 papers, 2008 to 2023). "The promotion of cell proliferation and migration by siRNA knockdown, as well as its effects by overexpression of the wild-type and mutant allele of IDH1, indicated that IDH1 may act as a tumor suppressor gene on hepatoma cell lines." (PMID 27469031, 2016). "Our in vitro cell experiment suggested that IDH1 may act as a tumor suppressor gene in hepatocellular carcinoma in that loss-of-function of IDH1 significantly promoted hepatoma cell growth and migration; whereas overexpression of wild-type IDH1 had opposite effects." (PMID 27469031, 2016). "The iCCA is considered the second most commonly diagnosed primary hepatic malignancy after hepatocellular carcinoma (HCC), presenting several genetic alterations, such as FGFR and IDH1/2 fusion, as well as ARID1A and BRAF mutations." (PMID 37958547, 2023). "The Idh1 promoter is activated by Srebf1a and Srebf2 in human hepatoma cells." (PMID 18959802, 2008).
kidney cancer (5 papers, 2015 to 2024). Primary or metastatic malignant neoplasm involving the kidney. "Similarly, down-regulation of IDH1 was detected in kidney cancer, which means the loss of IDH1 expression might contribute ccRCC genesis." (PMID 30153799, 2018). "We first found that IDH1 expression in normal kidney tissues and cell lines was significantly higher than that in kidney cancer tissues and cell lines, and so was its substrate α-KG." (PMID 33867843, 2021).
meningioma (5 papers, 2017 to 2025). A generally slow growing tumor attached to the dura mater. "Simple IHC-based diagnostics, similar to the IDH1 R132H antibody stepwise approach for IDH mutation, would be desirable - especially for meningioma - due to its speed in diagnostics and usefulness in settings with less resources." (PMID 36685704, 2023). "The sequencing test was successful in six meningiomas, all demonstrating wt IDH1 sequence." (PMID 36810519, 2023). "The observed cross-reaction with fibrous elements in meningioma cases has been previously identified as nonspecific binding by anti-IDH1 R132H to extracellular matrix protein or a subtype of collagen fiber." (PMID 31548536, 2017).
multiple myeloma (5 papers, 2019 to 2025). "One out of two solitary plasmacytoma cases was positive for BRAFV600E (BRAF:c.1799 T > A, p.(Val600Glu)) mutation and one out of four AL amyloidosis cases showed an isolated IDH1 mutation." (PMID 36138464, 2022).
Myelodysplasia (5 papers, 2020 to 2025). Clonal hematopoietic stem cell disorders characterized by dysplasia (ineffective production) in one or more hematopoietic cell lineages, leading to anemia and cytopenia. "Our data also supported the preleukemic nature of IDH1/2 mutations, but the persistence of IDH1/2 mutations (VAF>2.5%) in complete remission was associated with adverse outcome, higher chance of relapse or the development of myelodysplasia." (PMID 34153064, 2021). "FLT3-ITD, NPM1, and IDH1/2 were the most mutated genes, while also high proportion of ASXL1 and RUNX1 mutations could be detected, indicating the high proportion of myelodysplasia-related AML." (PMID 39453477, 2025). "Interestingly, the variation of allelic frequency of mutant IDH1 mutations is frequently high when associated with RTK pathway mutations, while the contrary when IDH1 mutations are associated with co-mutations typically related to clonal hematopoiesis and or myelodysplasia." (PMID 32859092, 2020).
spinal cord astrocytoma (5 papers, 2020 to 2021). A low or high grade astrocytoma that arises in the spinal cord. "Although IDH1 mutations frequently occur in brain astrocytomas and rarely in pediatric age, the incidence of IDH1 mutations in spinal cord astrocytomas has been found to be rather low, excluding enasidenib and ivosidenib from potential therapies." (PMID 34574050, 2021). "Although IDH1 mutations frequently occur in brain astrocytomas, the incidence of IDH1 mutations in spinal cord astrocytomas has been found to be rather low." (PMID 32228694, 2020). "A small group of spinal cord astrocytomas harbors isocitrate dehydrogenase (IDH) mutations, namely, IDH1 or IDH2 mutations." (PMID 34685506, 2021). "No IDH1 mutations were observed in two previous studies of nine and 17 grade II/III spinal cord astrocytomas." (PMID 32228694, 2020).
viral infection (5 papers, 2015 to 2023). "Viral infection promoted the expression of IDH1/2, which facilitates viral replication, and lipid synthesis is crucial for the maturation of viral particles." (PMID 37958486, 2023). "Exogenous G6PD or IDH1 expression inhibited the expression of HSCARG, resulting in increased expression of TNF-α and MX1 and reduced viral gene expression upon virus infection." (PMID 26694452, 2015).
acute promyelocytic leukemia (4 papers, 2012 to 2024). An aggressive form of acute myeloid leukemia (AML), characterized by arrest of leukocyte differentiation at the promyelocyte stage, due to a specific chromosomal translocation t(15;17) in myeloid cells. "Interestingly, we observed that both IDH1 and IDH2 mutations were predominantly found in AML with maturation (AML-M2; n = 24/44) and acute promyelocytic leukemia (APL) (AML-M3; n = 11/44) which were different from AML-M1 as reported by others." (PMID 22397365, 2012). "Elimination of IDH1 in human acute promyelocytic leukemia (APL) resulted in a phenotype similar to that observed with griseofulvin B (GCN B) treatment, one of the most common active secondary metabolites with potent antitumor activities." (PMID 36497259, 2022).
bladder cancer (4 papers, 2010 to 2025). "Although IDH1/IDH2 mutations are relatively rare in bladder cancer (∼2%), their dysfunction has notable ‘metabolite–epigenetic’ cascade effects: mutant IDH1 (e.g., R132H) loses its normal catalytic activity and instead produces high levels of 2-hydroxyglutarate (2-HG) in an NADPH-dependent manner." (PMID 41438986, 2025). "Tissue biopsies of late-stage bladder cancers also showed IDH1 downregulation compared with early-stage bladder cancers." (PMID 20459648, 2010).
chondroma (4 papers, 2021 to 2024). A benign well circumscribed neoplasm of hyaline cartilage arising from bone or soft tissue. "Since IDH1/IDH2 mutations were detected in both isolated chondromas and tumors removed from patients with multiple lesions (OD/MS)." (PMID 35765075, 2022). "In the analysis of six benign intracranial chondromas, IDH1 mutations were detected in 4/6 (66%)." (PMID 38248076, 2024). "Another important aim was to determine the IDH mutational status in a series of 96 intracranial chondroid tumors, including chondrosarcomas, chordomas, osteosarcomas, chondromas, and chondromyxoid fibromas in order to evaluate the diagnostic utility of IDH1/2 mutations for these types of neoplasms." (PMID 38248076, 2024). "In benign tumors, IDH1 mutations were present in chondroma (4/6), but absent in chondromyxoid fibroma (0/4)." (PMID 38248076, 2024).
chordoma (4 papers, 2013 to 2024). Chordomas are rare malignant tumors arising from embryonic remnants of the notochord in axial skeleton. "The IDH1 mutations were also found in 2/15 chordomas; both samples positive for the IDH1 mutation histologically were diagnosed as chondroid chordoma." (PMID 38248076, 2024). "The high frequency of IDH1/2 mutations in skull base chondrosarcoma makes it a useful diagnostic tool to differentiate from chordoma, particularly in small biopsy specimens." (PMID 34085407, 2021). "In our study, two IDH1-positive cases were found among 15 chordoma specimens, which can be interpreted as misdiagnosed tumors." (PMID 38248076, 2024).
diabetes (4 papers, 2015 to 2023). "The observation of abnormal threonine metabolism to 2,3-DHBA in both children and a dog with IDDM raises the question as to whether or not our observations of elevated plasma 2,3-DHBA in AML with mutated IDH1/2 could be due to diabetes." (PMID 33019704, 2020). "Hexokinase 2 (HK2; FC = −3.4), succinate dehydrogenase complex, subunit C (SDHC; FC = −3.1), isocitrate dehydrogenase 1 (IDH1; FC = −1.8), and pyruvate kinase muscle (PKM; FC = 1.5) were all downregulated in individuals with diabetes." (PMID 34690929, 2021). "Furthermore, IDH1 production of NADPH in the cytoplasm reduces intracellular oxidative stress, which as a complication of diabetes can also lead to osteoporosis." (PMID 37645416, 2023).
epileptic seizures (4 papers, 2018 to 2024). "Mutations of IDH1 are associated with better outcome, substantially increased risk of developing epileptic seizures, and cause a CPG-island hypermethylation phenotype that is associated with the proneural subtype of glioma." (PMID 30297697, 2018). "However, given that the frequency of IDH mutation in LGG approaches 80% and its possible role in epileptogenesis, a partial explanation for the observed higher frequency of epileptic seizures in LGGs could be due to IDH1 mutation status." (PMID 29687214, 2018).
esophageal squamous cell carcinoma (4 papers, 2016 to 2019). Esophageal squamous cell carcinoma (ESCC) is a type of esophageal carcinoma (EC) that can affect any part of the esophagus, but is usually located in the upper or middle third. "We aimed to investigate the pattern of expression and clinical significance of isocitrate dehydrogenase 1(IDH1) in esophageal squamous cell carcinoma (ESCC)." (PMID 27863386, 2016).
essential thrombocythemia (4 papers, 2016 to 2021). A chronic myeloproliferative neoplasm that involves primarily the megakaryocytic lineage. "IDH1 and TET2 frequencies were 5% in essential thrombocythemia (ET) and 1.7% in ET and 5% in primary myelofibrosis (PMF), respectively." (PMID 28218607, 2017).
glioneuronal tumors (4 papers, 2017 to 2022). "To achieve this goal, we evaluated BRAF and FGFR1 mdPCR assays in low grade glial or glioneuronal tumors and H3F3A, IDH1/2 and pTERT mdPCR assays in diffuse gliomas." (PMID 33282733, 2020).
Hepatitis (4 papers, 2018 to 2024). Inflammation of the liver. "Research from 2019 found IDH1 mutations in 13% of iCCA patients and 0.8% in eCCA patients, with IDH-1 mutations more prevalent in non-hepatitis CCA patients." (PMID 39199633, 2024). "Another study demonstrated a higher IDH1/2 mutation prevalence in patients without hepatitis compared to those with hepatitis (20% vs. 2%, respectively)." (PMID 32824685, 2020). "Similarly, a molecular study on 97 liver cancers with biliary phenotype reported a higher recurrence rate of KRAS (20%) and IDH1/2 (20%) mutations in hepatitis-negative patients, compared to hepatitis-positive patients." (PMID 37174616, 2023).
hyperlipidemia (4 papers, 2014 to 2021). "IDH1 transgenic mice exhibit fatty liver, hyperlipidemia and obesity." (PMID 25739786, 2015).
lymph node metastasis (4 papers, 2016 to 2025). "Liu and colleagues also reported that a low expression level of IDH1 significantly correlated to advanced-stage lymph node metastasis and poor disease survival." (PMID 39940737, 2025). "Some investigators have found that IDH1/2 mutation was correlated to several clinical characteristics in ICCs, such as lower level of CA19–9, lower incidence of lymph node metastasis and smaller size of tumors." (PMID 32293336, 2020). "Since IDH1/2 mutations were typically detected in small duct type of ICCs, we considered these factors (CA19–9, lymph node metastasis and size of tumor) might be associated with small duct type, rather than IDH1/2 mutation." (PMID 32293336, 2020).
neuroblastoma (4 papers, 2015 to 2024). Neuroblastoma (NB) is the most common solid, extracranial childhood tumor. "In agreement with our results, previous studies have reported that enhanced c-Myc and N-Myc expression makes neuroblastoma and B-cells addicted to glutamine and suppression of glutamine metabolism, by inhibition of IDH1, IDH2 or GLS expression reduces cellular proliferation and tumor growth." (PMID 28430666, 2017).
pheochromocytoma (4 papers, 2017 to 2021). "In paragangliomas, a mutation in IDH1 was first recorded during the analysis of 365 samples and a somatic mutation in this gene was detected in carotid paraganglioma although no IDH mutations were found in pheochromocytomas." (PMID 28187001, 2017).
renal cell carcinoma (4 papers, 2019 to 2022). "The purpose of our study was to explore the effect and intrinsic mechanism of wild-type IDH1 and its substrate α-KG on renal cell carcinoma (RCC)." (PMID 33867843, 2021). "Wild-type IDH1 suppresses tumor development in renal cell carcinoma via degrading HIF-α." (PMID 35924146, 2022).
skin cancer (4 papers, 2017 to 2023). "IDH1 expression dysregulation is observed in many cancer types, and a decrease in IDH1 expression is highly correlated with the pathogenesis of early skin tumors." (PMID 32602849, 2020). "We discovered that 7 of 11 IDH1-mutated tumours were also ATRX-mutated (28-fold enrichment compared to IDH1 WT skin cancers; p = 1.2 × 10−8, Fisher’s exact test) and that both ATRX and IDH1 were predominantly hit by somatic mutations (14 of 15 for ATRX, 7 of 11 for IDH1)." (PMID 36883553, 2023).
atherosclerosis (3 papers, 2022 to 2023). A disease characterized by the build-up of fatty material and calcium deposition in the arterial wall resulting in partial or complete occlusion of the arterial lumen. "The inhibition of IDH1 modulates the progression of atherosclerosis by ameliorating macrophage viability and apoptosis." (PMID 36290297, 2022). "Inhibiting macrophage ferroptosis and foam cell formation by knocking down IDH1 is a promising study direction for better understanding the occurrence and progression of atherosclerosis, as well as the treatment targets for atherosclerosis." (PMID 36290297, 2022). "Ox-LDL-induced macrophage damage and apoptosis are critical in the formation and development of atherosclerosis, and inhibiting IDH1 expression in macrophages prevented viability and apoptosis death in our work." (PMID 36290297, 2022). "In our findings, knocking down IDH1 inhibited macrophage ferroptosis and foam cell formation, which is a potential research area for better understanding the occurrence and development of atherosclerosis." (PMID 36290297, 2022). "However, it has been demonstrated that IDH1 inhibition regulates the progression of atherosclerosis by improving macrophage viability and apoptosis, and may alleviate atherosclerosis by activating NRF2 to ameliorate ox-LDL-induced ferroptosis in macrophages." (PMID 37645416, 2023). "Furthermore, inhibiting IDH1 may alleviate atherosclerosis by ameliorating ox-LDL-induced macrophage ferroptosis by activating NRF2." (PMID 36290297, 2022). "We have demonstrated that inhibiting IDH1 reduces ox-LDL-induced ferroptosis and foam cell formation in macrophages, implying that IDH1 may be an important molecule regulating foam cell formation and may be a promising molecular target for the treatment of atherosclerosis." (PMID 36290297, 2022). "However, it is unknown whether IDH1 enhances ferroptosis and thus worsens atherosclerosis progression." (PMID 36290297, 2022). "However, it is unclear whether IDH1 reduces ox-LDL-induced ferroptosis and, as a result, influences the progression of atherosclerosis." (PMID 36290297, 2022).
benign cartilage tumors (3 papers, 2015 to 2024). "Isocitrate dehydrogenase (IDH) mutations are involved in the pathogenesis of a variety of neoplasms, and recently, IDH1/2 mutations have been found in the tissue of benign cartilage tumors as well as in conventional chondrosarcomas and highly aggressive dedifferentiated chondrosarcomas." (PMID 38170705, 2024). "The high frequency of IDH1 and IDH2 (collectively referred to as IDH) mutations in benign cartilage tumours indicates that these mutations occur early in tumourigenesis, suggesting that IDH mutations have an important driver role in the formation of cartilage tumours." (PMID 37509266, 2023).
brain astrocytoma (3 papers, 2020 to 2021). A astrocytoma (excluding glioblastoma) that involves the brain. "In contrast to brain astrocytomas, no hotspot IDH1 p.R132H or IDH2 p.R172H mutations were identified, and none of our cases harbored the 1p19q codeletion." (PMID 32771057, 2020).
central neurocytoma (3 papers, 2013 to 2025). A benign brain tumor composed of neural elements which most often arise from the SEPTUM PELLUCIDUM and the walls of the lateral ventricles. "All observed neurocytomas (central, n=35; extraventricular, n=4) were negative for mutated IDH1 protein." (PMID 24179531, 2013).
cervical carcinoma (3 papers, 2021 to 2025). A carcinoma arising from either the exocervical squamous epithelium or the endocervical glandular epithelium. "Future studies should aim to dissect the functional interplay between IMP3 and IDH1, thereby elucidating its role in mitochondrial metabolic regulation and its broader implications for cervical cancer initiation and progression." (PMID 41614778, 2025).
chondroblastic osteosarcoma (3 papers, 2013 to 2021). An osteosarcoma characterized by the presence of atypical cartilage of variable cellularity. "The presence of IDH mutations can also be used in differential diagnostic between dedifferentiated CHS and undifferentiated pleomorphic sarcoma of bone (UPS) or high-grade CHS and chondroblastic osteosarcoma, where UPS and chondroblastic osteosarcoma lack IDH1/2 mutations." (PMID 34069269, 2021).
Cirrhosis (3 papers, 2017 to 2022). A chronic disorder of the liver in which liver tissue becomes scarred and is partially replaced by regenerative nodules and fibrotic tissue resulting in loss of liver function. "Multivariate analysis showed the presence of IDH1 mutation was associated with poor prognosis of HCC patients, independently of tumor stage, sex, age at diagnosis, HBV infection, and cirrhosis." (PMID 28403884, 2017).
clear cell renal cell carcinoma (3 papers, 2017 to 2020). "Studying IDH1/2 mutations in clear cell renal cell carcinomas (RCCs) demonstrated that IDH1 is mutated in only 4 of 833 cases (0.5%) and no IDH2 mutations." (PMID 28403884, 2017). "The purpose of this study was to investigate the role of isocitrate dehydrogenase 1 (IDH1) expression on prognosis of patients with clear cell renal cell carcinoma (ccRCC) following nephrectomy." (PMID 30153799, 2018).
cognitive deficits (3 papers, 2022 to 2023). "Another study,29aiming to investigate the effect of IDH1 mutation on the structural connectome, has shown that wild-type tumor patients demonstrate lower network efficiency and more frequent cognitive impairment than mutant ones." (PMID 36970174, 2023). "For example, fewer cognitive deficits are found in patients with an Isocitrate Dehydrogenase (IDH) 1 or 2 mutation compared to patients with an IDH1 wild-type tumor." (PMID 36138995, 2022). "Of note, IDH-1 and ATRX mutations are also associated with cognitive deficits." (PMID 35148403, 2022).